CXCL13 (C-X-C motif chemokine ligand 13)
Diseases named in the same sentence as CXCL13 in open-access papers (continued):
Sharing a sentence is not in itself a finding about the gene and the disease.
idiopathic pulmonary fibrosis (19 papers, 2015 to 2025). Idiopathic pulmonary fibrosis (IPF) is a nonneoplastic pulmonary disease that is characterized by the formation of scar tissue within the lungs in the absence of any known cause. "CXCL13 is a proinflammatory chemokine involved in B cell activation and antibody maturation, associated with idiopathic pulmonary fibrosis." (PMID 34858405, 2021). "Of note, HGF is a pleiotropic cytokine with anti-inflammatory properties playing a fundamental role in lung tissue repair, and CXCL13, a pro-inflammatory chemokine associated with pulmonary fibrosis and regulating the maturation of B cell response." (PMID 34373466, 2021). "CXCL13 is implicated in pulmonary fibrosis and the regulation of B-cell response." (PMID 38543303, 2024). "Dysregulated CXCL13 expression has been associated with various human diseases, such as cancers, infectious diseases, idiopathic pulmonary fibrosis (IPF), transplantation rejection, and neuropathic pain." (PMID 35309354, 2022). "In one fatal and irreversible interstitial lung disease, idiopathic pulmonary fibrosis, CXCL13 is produced by CD68- and CD206-positive alveolar macrophages, and the serum CXCL13 concentration predicts the progression and severity of the disease." (PMID 34947813, 2021). "CXCL13 is abnormally expressed in the lung tissues of patients with idiopathic pulmonary fibrosis (IPF), and its circulating concentration is also highly correlated with the clinical manifestations and disease progression of individual patients." (PMID 32969837, 2020). "CXCL13 and CXCR5 are key players in the trafficking of B-cells, and CXCL13 serum levels are increased in various autoimmune disorders as well as in patients with idiopathic pulmonary fibrosis." (PMID 26927848, 2016). "As reported, CXCL13 is up-regulated in the lungs and plasma of idiopathic pulmonary fibrosis patients, and the extent of CXCL13 overexpression is correlated with cumulative survival." (PMID 26517519, 2015). "Biomarkers previously associated with pathobiology and/or progression in pulmonary fibrosis were selected to reflect cellular senescence (telomere length), pulmonary epithelium (SP-D, RAGE), myeloid activation (CXCL13, YKL40, CCL18, OPN) and fibroblast activation (POSTN, COMP, PROC3)." (PMID 38753183, 2024). "However, the persistence of elevated levels of CXCL13 in the lung tissue and serum may be detrimental and responsible for fueling the inflammation and promoting lung fibrosis." (PMID 34373466, 2021). "Therefore, CXCL-13 in serum can be used as an early marker for the diagnosis of pulmonary fibrosis." (PMID 33101446, 2020). "Recently, CXCL13, a ligand of CXCR5, has been reported to increase in the peripheral blood and lungs of patients with idiopathic pulmonary fibrosis (IPF)." (PMID 31694639, 2019). ",55,57, 58, 59 These findings coupled with those of multiple other studies showing that biomarkers of immune dysregulation such as serum levels of chemokine (C-X-C motif) ligand 13 (CXCL13) and chemokine ligand 18 (CCL18) can predict pulmonary fibrosis progression reliably." (PMID 39521375, 2025). "The lack of changes in Cxcl13, Ccl11, Ccl19, Xcl1, and Cxcl5 mRNA levels may be due to differences in bleomycin-induced pulmonary fibrosis and IPF, although models of bleomycin-induced pulmonary fibrosis are the most common experimental models for investigating IPF." (PMID 37122736, 2023).
Arthritis (17 papers, 2012 to 2025). Inflammation of a joint. "Lyz1, Dnajc15, Nfkbia, Cxcl12, Ccl21a, and Cxcl13 are considered to be arthritis-associated gene." (PMID 33752715, 2021). "The 1,407 genes with increased expression in DA and reciprocally decreased expression in DA.F344(Cia5a) congenics included pro-inflammatory cytokines and chemokines implicated in arthritis pathogenesis such as Il1b (5.17-fold on microarray, and 2.46-fold on qPCR), Il18, Mif, Ccl2, Ccl7 and Cxcl13." (PMID 23249408, 2012). "The anti-TNF/IL-6 bispecific antibody completely inhibits the inflammatory factor CXCL13 in the arthritis model, and its effect is superior to that of the monoclonal antibody combination." (PMID 40932933, 2025). "Flow cytometry analysis revealed an increase of CD19+IgM+CD5+ cell population in draining lymph nodes and an increase of CD19+CD21hiCD23hi (B regulatory) cells in APRIL-Tg mice with arthritis as well as an increase of IL-10 and CXCL13 production in vitro." (PMID 38691538, 2024). "Collapsed PLNs in Advanced arthritis are characterized by translocated Bin cells into the sinuses, presumably via a CXCL13 gradient produced by stagnant macrophages that cannot egress due to the lack of lymphatic vessel contractions and passive flow." (PMID 37691918, 2023). "In NSG-RA mice, in vivo signs of arthritis as well as the expression of murine Saa1 and Cxcl13 in the joints increased upon challenge, whereas the development of histopathological alterations and the secretion of inflammatory plasma cytokines occurred spontaneously, without challenge." (PMID 40977310, 2025). "We also quantified CXCL12 and CXCL13 levels in the serum at the same time point of arthritis." (PMID 38691538, 2024). "However, in ulcerative colitis rheumatoid and arthritis lesions, CXCL13 was mainly produced by macrophages instead of FDCs and stromal cells." (PMID 37047294, 2023). "Cxcl13 may mediate recruitment of immune cells to infected joints during infection, but since the MyD88−/− mice (which have reduced expression of Cxcl13) still develop arthritis, this suggests that other chemokines may also play significant roles." (PMID 24967215, 2014). "In Early arthritis, the CD23+/CD21hi Bin cells accumulate in PLN follicles while afferent CXCL13-expressing macrophages egress through the expanded sinuses." (PMID 37691918, 2023). "Inhibition of CXCL13 using an short hairpin RNA (shRNA) in collagen-induced arthritis (CIA) mice markedly reduced EPC homing, angiogenesis, and arthritis severity." (PMID 35309354, 2022). "The receptors and their ligand CXCL13 and CCL20 have been suggested to be important for B-cell migration into the inflamed synovium in human arthritis, and CCR6 has been reported to be increased in peripheral B cells from arthritis patients." (PMID 31882654, 2019). "In an exploratory analysis, patients with SLE with arthritis (according to the ACR criteria) had increased levels of both CXCL10 and CXCL13." (PMID 30092845, 2018). "However, in ulcerative colitis rheumatoid and arthritis lesions, CXCL13 was produced in macrophages but not in FDCs and stromal cells." (PMID 37047294, 2023). "Taken together, these results support the contention that CXCL13 and CCL20, acting synergistically, may constitute a key driving force for the migration and recruitment of B lymphocytes in the inflamed synovium of patients with arthritis." (PMID 29880013, 2018). "Based on CXCR5 and CCR6 internalization and B-cell migration experiments, our results suggest that CXCL13 and CCL20, the respective ligands of CXCR5 and CCR6, by acting synergistically, might participate in the recruitment of B cells in the synovium in patients with arthritis." (PMID 29880013, 2018).
influenza (17 papers, 2019 to 2025). An acute viral infection of the respiratory tract, occurring in isolated cases, in epidemics, or in pandemics; it is caused by serologically different strains of viruses (influenzaviruses) designated A, B, and C, has a 3-day incubation period, and usually lasts for 3 to 10 days. "Elevated plasma CXCL13 levels have previously been linked to antibody production after influenza vaccination." (PMID 40766325, 2025). "Together, the data suggest that CXCL5 deficiency induced CXCL13 expression in pulmonary CD64+ macrophages/monocytes in influenza-infected lungs beginning in the early innate immunity stage." (PMID 34868067, 2021). "The essential requirement for CXCL13 or CCL19/21 in influenza‐induced pulmonary TLSs has been dissected in splenectomized mice lacking CXCL13 and/or CCL19/21 (paucity of lymph node T cells, plt/plt)." (PMID 40884054, 2025). "During influenza infection, type I IFNs induce CXCL13 expression in a phenotypically distinct subset of pulmonary PDGFRα+ fibroblasts." (PMID 40815083, 2025). "Type I IFN is highly induced in influenza infection and can directly induce Cxcl13 expression by primary lung fibroblasts in vitro." (PMID 40884054, 2025). "In comparison, influenza infection induces CXCL13 independently of IL‐17 in the adult but seems to require IL‐17 in the neonatal lung." (PMID 40884054, 2025). "Presently, we have observed that CXCL13 significantly augments both the breadth and magnitude of antibody responses against influenza and SARS-CoV-2 viruses." (PMID 39436660, 2024). "The finding that loss of CXCL5 signaling triggers CXCL13 expression in CD64+ macrophages/monocytes in influenza-infected mouse lungs suggests that CXCL5 negatively regulates CXCL13 expression in macrophages." (PMID 34868067, 2021). "It seems that the pulmonary immune system controls abundant CXCL13 expression from a large number of macrophages during the anti-influenza innate immune response." (PMID 34868067, 2021). "The findings suggest that macrophages are the key leukocytes in the pathway by which CXCL5 controls CXCL13 expression during influenza infection." (PMID 34868067, 2021). "CXCL13 has been reported to be expressed in infected lungs after influenza infection, and lung fibroblasts are the primary cells of CXCL13 production 5 d.p.i.." (PMID 34868067, 2021). "Influenza challenge induced considerable expression of CXCL13 mRNA and production of CXCL13 protein in the culture supernatants of the AMs." (PMID 34868067, 2021). "Influenza infection induces pulmonary CXCL13 expression by type I IFN-activated lung fibroblasts; however, the levels of pulmonary IFN-α/β were comparable between WT and CXCL5-/- infected mice." (PMID 34868067, 2021). "IL-17 is critical for recruiting B cells to the lung in response to influenza infection by inducing CXCL13 expression." (PMID 33562141, 2021). "In a model of influenza infection, type I interferons induced CXCL13 production in lung fibroblasts, which resulted in the development of TLS." (PMID 35145509, 2021). "Inhibition of CXCL5-CXCR2 axis markedly induces CXCL13 expression in CD64+CD44hiCD274hi macrophages/monocytes in infected lungs, and in vitro administration of CXCL5 to CD64+ alveolar macrophages suppresses CXCL13 expression via the CXCL5-CXCR2 axis upon influenza challenge." (PMID 34868067, 2021). "Therefore, it is likely that activated CXCR2 signaling restricts CXCL13 expression in influenza-infected AMs via the intracellular pathway, especially the PI3K/AKT cascade." (PMID 34868067, 2021). "In addition to regulating neutrophil chemokine levels in the influenza infection mouse model, CXCL5 has also been found to regulate the expression of another chemokine, CXCL13, a predominant B cell chemoattractant, in infected lungs after influenza infection." (PMID 34868067, 2021).
influenza (continued). "Furthermore, the levels of CXCL13 in the culture supernatants of influenza-infected macrophages were significantly decreased upon the addition of recombinant CXCL5, recombinant CXCL1 and CXCL2, or all the proteins combined." (PMID 34868067, 2021). "The observed high expression of these surface markers indicated that a reduced CXCR2 signaling caused pulmonary macrophages surrounded by an innate immune microenvironment induced by influenza infection to convert into M2-like macrophages that possibly produced CXCL13." (PMID 34868067, 2021). "Indeed, mice deficient in both LTα and TNF express CXCL13 in the lung in response to influenza infection, despite no expression in SLOs." (PMID 40884054, 2025). "Nasal immunization with CTA1-3M2e-DD in adult mice stimulated robust heterosubtypic protection against influenza infection, while CTA1-DD greatly up-regulated the expression of the Cxcl13 gene." (PMID 39436660, 2024). "Further in vitro studies demonstrated that influenza virus infection induced CXCL13 expression in AMs and that CXCL5 administration inhibited CXCL13 expression in influenza-infected AMs." (PMID 34868067, 2021). "Of the 638 antiviral and inflammatory genes that were differentially expressed between lungs of uninfected macaques and macaques with lethal influenza, 541 (85%) were upregulated in response to infection, including inflammatory chemokines such as CXCL10 and CXCL13 and a cluster of IFN genes." (PMID 35271686, 2022). "The local expression of homeostatic chemokines, including C-X-C motif chemokine ligand 13 (CXCL13), chemokine (C–C motif) ligand 19 (CCL19), and CCL21, induces the formation of iBALT following influenza infection and plays an important role in providing an effective immune response." (PMID 35893822, 2022). "Responders showed a higher expression of CXCL13 compared with non-responders and might be contributing to influenza-specific antibody production as characterized by this group." (PMID 38543937, 2024). "Also, as expected based on past work showing the importance of antigen‐presenting DCs for generation of a vaccination response, there was a significant reduction in levels of anti‐influenza HA‐specific IgG and CXCL13 when DCs were not included in the LF chips." (PMID 35289122, 2022). "Here, using an influenza (H1N1) infected CXCL5-/- mouse model, we found that CXCL5 not only responds to neutrophil infiltration into infected lungs at the innate immunity stage, but also affects B lymphocyte accumulation in the lungs by regulating the expression of the B cell chemokine CXCL13." (PMID 34868067, 2021). "We found that after correction for sex and age, the immune characteristics of the responders after influenza immunisation were lower concentrations of IgM, GZMB and IL12, and a higher concentration of CXCL13, in comparison with those of the non-responders." (PMID 38543937, 2024). "In contrast, the expression of CXCL13 increased markedly in the group treated with CXCL5 and CXCR2 antagonists compared to the group without the CXCR2 antagonist upon influenza challenge." (PMID 34868067, 2021). "Thus, the serological non-responders after influenza immunisation seemed to be characterized by cell-mediated immunity with higher levels of total IgM, GZMB and IL12, and lower levels of CXCL13 than the responders." (PMID 38543937, 2024).
non-small cell lung carcinoma (16 papers, 2014 to 2025). A group of at least three distinct histological types of lung cancer, including non-small cell squamous cell carcinoma, adenocarcinoma, and large cell carcinoma. "Additionally, the findings suggest that elevated relative expression of CXCL13 in cases of malignant pleural effusion caused by non-small cell lung cancer may indicate a poor prognosis." (PMID 37025603, 2023). "The crucial role of the chemokine CXCL13 has been demonstrated in non-small cell lung cancer and esophageal squamous cell carcinoma, while its predictive role in neoadjuvant immunotherapy for CRC remains to be explored." (PMID 40242245, 2025). "Previous studies have shown that 70% of non-small cell lung cancer (NSCLC) patients from highly polluted areas in China exhibited high levels of CXCL13 expression in the tumor tissue." (PMID 34553036, 2021). "A significant correlation between CXCL13 expression and TLS presence was identified, consistent with findings in other cancers such as esophageal squamous cell carcinoma, non-small-cell lung carcinoma, stomach adenocarcinoma, and malignant mesothelioma." (PMID 40352278, 2025). "Certain immune or stromal cells can secrete CXCL13 to act like lymphoid tissue organizer (LTo) cells, such as CD8+ T cells in non-small-cell lung cancer (NSCLC), TFH cells, and fibroblasts in breast cancer." (PMID 39456558, 2024). "Previous reports showed that, for non-small cell lung cancer (NSCLC) patients, the tumor sites express high levels of chemokine CXCL13, whereas CXCR5, the only receptor for CXCL13, is mainly expressed on B cells and follicle helper T cells." (PMID 34553036, 2021). "A comparative analysis of an inflammatory signature in non-small cell lung cancer (NSCLC) and chronic obstructive pulmonary disease (COPD) patients revealed that CXCL13 was included among the chemokines elevated in NSCLC patients." (PMID 31354634, 2019). "CXCL13 expression has been correlated with TLS rates in esophageal squamous cell carcinoma, non-small-cell lung carcinoma, stomach adenocarcinoma, and malignant mesothelioma, and it has been suggested as a predictive marker for immune checkpoint inhibitor-responsive bladder cancer." (PMID 40352278, 2025).
clear cell renal cell carcinoma (15 papers, 2018 to 2026). "In contrast, CXCL13 was significantly upregulated in clear cell renal cell carcinoma, and high CXCL13 expression was associated with a poor prognosis." (PMID 35141160, 2022). "However, in clear cell renal cell carcinoma, elevated CXCL13 expression is associated with poorer progression-free survival and overall survival." (PMID 40352278, 2025). "In clear cell renal cell carcinoma, T cells secreting CXCL13 infiltrate tumor tissues, expressing exhaustion markers like T‐cell immunoglobulin mucin 3 and programmed cell death protein 1 on their cell surface." (PMID 39344390, 2024). "A very recent study showed significant CXCL13 up-regulation in clear renal cell carcinoma (ccRCC) that correlates with advanced disease stage and poor prognosis, together with elevated CXCL13 serum levels in ccRCC patients." (PMID 31354634, 2019). "In clear cell renal cell carcinoma (ccRCC), TLSs correlate with improved survival and enhanced immunotherapy responses, although elevated CXCL13 expression may paradoxically signal more aggressive disease." (PMID 41821902, 2026).
lupus nephritis (15 papers, 2014 to 2026). Glomerulonephritis in the context of systemic lupus erythematosus. "In these animals, B cell recruitment occurs during the development of lupus nephritis and is associated with abnormal expression of CXCL13 and adhesion molecules, such as PNAd, ICAM and VCAM-1 in the blood vessels of PVS." (PMID 39483979, 2024). "Podocytes produce proinflammatory mediators upon stimulation through CXCL13, indicating it might be another pathogenic factor of lupus nephritis." (PMID 35371102, 2022). "In pathological conditions such as lupus nephritis, ectopically overexpressed CXCL13 acts as a potent pro-inflammatory chemokine, regulating the migration of immune cells such as B lymphocytes and T lymphocytes to sites of inflammation." (PMID 41164191, 2025). "The chemokine CXCL13, which is produced during lupus nephritis, has been analyzed as a new SLE and lupus nephritis biomarker." (PMID 38001978, 2023). "This evidence underscores the pathogenic importance of monocyte-derived MF and their expression of Cxcl13 in the development of lupus nephritis." (PMID 35371102, 2022). "It was reported that proteoglycan biglycan induced CXCL13 expression and aggravated lupus nephritis in mice through TLR2/4 on macrophages and dendritic cells." (PMID 32111963, 2020). "Cxcl13 has been described in the formation of B cell infiltrates in acute renal transplant rejection, interstitial nephritis and IgA nephropathy as well as in an animal model of lupus nephritis." (PMID 41384828, 2025). "CXCL13 was considerably upregulated in the kidney tissues of LN patients, which might be a therapeutic target in glomerulonephritis and SLE nephritis." (PMID 34721432, 2021). "Regarding lupus nephritis, the serum B lymphocyte chemoattractant (CXCL13/BLC) was increased in 31 adult patients in comparison with 60 SLE patients without renal involvement and might be a surrogate available marker as well." (PMID 24692841, 2014). "The expression level of chemokines like CXCL11—Interferon-inducible T cell α-chemoattractant (I-TAC), CXCL13—B-lymphocyte chemoattractant (BLC), CXCL10 (IP-10) and CCL3 (MIPα), correlate with disease activity (especially lupus nephritis (LN))." (PMID 26473848, 2015).